GDF15 (growth differentiation factor 15)
Diseases named in the same sentence as GDF15 in open-access papers (continued):
Sharing a sentence is not in itself a finding about the gene and the disease.
Anorexia (continued). "One possibility is that elevated levels of circulating GDF-15 are associated with cachectic symptoms, including loss of skeletal muscle mass, systemic inflammatory reaction, poor PS, anorexia, and shortened survival time." (PMID 34638326, 2021). "When calculating overall energy balance, this loss of GDF15-dependent day time anorexia together with a preserved elevated night time energy intake proved sufficient to explain the progressive fat accumulation that we observed in Gdf15 ablated UCP1-tg mice." (PMID 33464381, 2021). "Local hypothalamic expression of GDF15 or intracerebroventricular injections of recombinant human GDF15 in mice resulted in a direct central action which induced anorexia and weight loss." (PMID 34043633, 2021). "Recent studies have found that GDF15 can induce anorexia and fat and lean body mass loss, and there appears to be a consistent correlation between an increase in the serum levels of GDF15 and a decrease in the markers of nutrition." (PMID 33178828, 2020). "Although different experimental studies converge on the role of GDF-15 as pivotal in determining anorexia and body weight loss, the evidence in humans is limited and apparently controversial." (PMID 33396237, 2020). "We explored the association(s) between GDF-15 serum levels and anorexia and, secondarily, with low muscle mass and body weight loss in cancer patients." (PMID 33396237, 2020). "The loss of GDF15‐dependent daytime‐restricted anorexia together with a preserved elevated night time energy intake thus drives the progressive fat accumulation observed in TGxKO mice." (PMID 32026535, 2020). "Further investigation of the causal nature of the relationship between glucocorticoid deficiency, elevated circulating levels of GDF15 and symptoms of anorexia, weight loss, nausea and vomiting is warranted." (PMID 31853550, 2020). "Blockade of GDF-11 prevented both anorexia and muscle loss, whereas inhibition of GDF-15 was most effective against anorexia." (PMID 32508832, 2020). "Therapeutically targeting the GDF15–GFRAL axis has gained considerable attention in the management of anorexia and cachexia associated with cancer and other chronic diseases." (PMID 31853550, 2020). "GDF-15 has been shown to contribute to appetite loss in xenograft mouse models of prostate cancer; and a direct correlation between increased serum GDF-15 levels and cancer-associated anorexia has been observed in prostate cancer patients." (PMID 32508832, 2020). "For this reason, we aimed to assess (i) primarily the association between GDF-15 circulating levels and anorexia and (ii) secondarily with low muscle mass or body weight loss in cancer patients naïve to anti-cancer treatments." (PMID 33396237, 2020). "In experimental animals, MIC-1/GDF15 levels of above 5,000–8,000 pg/mL cause severe anorexia/cachexia because of actions on feeding centres in the brainstem and hypothalamus." (PMID 26207898, 2015). "Because of its effects on feeding centres within the brain, elevation in serum levels of MIC-1/GDF15 is an important cause of cancer-associated anorexia/cachexia." (PMID 22952779, 2012). "To date, a debate continues whether GDF15 induces anorexia and weight loss solely activating central receptors, or by engaging in a wider network of gut‐brain regulation factors." (PMID 40708105, 2026). "Additionally, in cancer field, several basic and clinical reports have shown GDF15 inducing anorexia and following weight loss." (PMID 41016991, 2026). "Therefore, targeting GDF-15 can be useful for the treatment of anorexia caused by cancer as well as the prevention of resulting weight loss." (PMID 39781722, 2025). "Notably, elevated serum GDF-15 levels are associated with poor prognosis and cancer cachexia, including anorexia as a characteristic symptom across tumour types, highlighting its role in cancer biology." (PMID 41294666, 2025). "GDF-15 levels are associated with distant metastasis, anorexia, and weight loss." (PMID 41294666, 2025).
Anorexia (continued). "Notably, GDF15 has been extensively studied in the context of metabolism regulation, appetite, weight loss, and anorexia." (PMID 40464681, 2025). "GDF-15 causes anorexia by influencing the central systems regulating metabolism and appetite." (PMID 39781722, 2025). "Therefore, GDF-15 presents itself as a potential therapeutic target for treating anorexia associated with cancer." (PMID 39781722, 2025). "Additionally, data indicate that GDF15 causes anorexia by inducing nausea and/or by engaging emetic neurocircuitry in the area postrema and nucleus tractus solitarius." (PMID 40562759, 2025). "Administration of exogenous GDF15 causes anorexia and CTA10,11,15." (PMID 39737892, 2024). "Additionally, we explored the possibility of enhancing the therapeutic effectiveness by combining TCMCB07 with an anti-GDF15 antibody to combat chemotherapy-induced anorexia and weight loss." (PMID 39509261, 2024). "These same models demonstrate that GDF15 neutralization alleviates anorexia and weight loss." (PMID 38146512, 2023). "Administration of recombinant GDF15 promoted weight loss due to anorexia in animal models." (PMID 36078078, 2022). "Thus, the MCT rat model presents with anorexia-associated body weight loss with increased circulating GDF15 and cytokine levels after MCT dosing." (PMID 35406637, 2022). "Recent data also suggest that GDF15 is involved in hyperemesis gravidarum, supporting the hypothesis that GDF15 triggers anorexia and subsequent weight loss, at least partly, through the induction of malaise." (PMID 35916366, 2022). "Notably, in cancer patients overexpressed GDF-15 was identified as a novel appetite regulator that causes anorexia and weight loss." (PMID 34247467, 2021). "Further evidence revealed that GDF15 signals via activation of cholecystokinin neurons in the area postrema and nucleus of the tractus solitarius may contribute to anorexia and body weight loss." (PMID 34925008, 2021). "GDF15 is a distant TGF-β family member that induces anorexia and weight loss." (PMID 33903632, 2021). "By our study design, we aimed to ascertain the association of the novel cytokine GDF-15 and anorexia during cancer and its potential relationship with low muscle mass and body weight loss, which are well known hallmarks of deranged nutritional and metabolic status in cancer." (PMID 33396237, 2020). "GFRAL was recently identified as a type of central nervous system receptor for mediating the anorectic actions of GDF-15, which could cause anorexia and weight loss in mice." (PMID 33201838, 2020). "Finally, another emerging factor contributing to anorexia is the growth differentiation factor 15 (GDF15), which has been linked to cancer-induced emesis." (PMID 33202621, 2020). "We hypothesized that GDF15 would be increased in the setting of glucocorticoid deficiency and may contribute to the nausea/vomiting/anorexia phenotype frequently observed in adrenal insufficiency." (PMID 31853550, 2020). "Experimental data indicated that GDF-15 may play a key role in the pathogenesis of cancer-related anorexia and therefore potentially implicated in determining protein-energy malnutrition." (PMID 33396237, 2020). "Indeed, the frailty syndrome is associated with anorexia and sarcopenia and has a number of biological correlates with cancer cachexia—in which there is a clear pathogenic role for GDF15." (PMID 32310257, 2020). "In addition, advanced age and frailty are associated with anorexia and sarcopenia and are associated with elevated circulating GDF15." (PMID 32310257, 2020). "High MIC-1/GDF15 serum levels may cause cancer anorexia/cachexia syndrome, a frequently observed complication of advanced cancer, which causes significant morbidity, predominantly by limiting therapy and accelerating demise." (PMID 24971956, 2014).
Anorexia (continued). "Consequently, It appears likely that the anorexia/cachexia associated with marked elevation of serum levels of MIC-1/GDF15, are due to the subversion of a physiological pathway for appetite regulation." (PMID 24971956, 2014). "Thus it would appear that diseases associated with marked increases in MIC-1/GDF15 expression subvert a normal physiological pathway to cause anorexia/cachexia." (PMID 23468844, 2013). "Recently, it has been shown that GDF-15 is a key regulator in anorexia, and weight and fat loss." (PMID 23800095, 2013). "GDF15 expression and secretion is upregulated in response to cellular stress 64,65, and elevated circulating levels have been identified in a broad range of human diseases, including cardiac, renal, and respiratory failure, and notably anorexia and weight loss 66–69." (PMID 37045997, 2023). "Furthermore, we investigated the causal role of GDF15 by assessing whether GDF15 blockade via a selective monoclonal antibody (mAb2) could prevent MCT-induced anorexia, weight loss, fat loss, and muscle atrophy in this preclinical cardiac cachexia model." (PMID 35406637, 2022). "GDF15 induces anorexia and visceral discomfort, regulating appetite, food intake and potentially metabolic responses." (PMID 40708105, 2026). "GDF15 has recently emerged as inducing anorexia and visceral malaise, as evaluated in animal models and patients with cancer." (PMID 40708105, 2026). "GDF15 levels decreased as the disease progressed, and its elecated levels correlated with anorexia symptoms." (PMID 40181460, 2025). "In animal models, GDF‐15 induces conditioned taste aversion in mice, pica behaviour in rats and emesis in musk shrews, mirroring cisplatin‐induced nausea and anorexia in cancer patients." (PMID 40343378, 2025). "Inhibition of GDF15 in mice and humans reverses cancer cachexia, including reducing anorexia and emesis, restoring muscle function as well as physical performance." (PMID 40562759, 2025). "This restoration of body weight was accompanied by significantly improved food intake in the POLG‐GDF15 mAB2 group compared with POLG‐Veh animals, validating that GDF15 neutralization improves appetite and ameliorates the anorexia phenotype in rodents." (PMID 39976232, 2025). "Notably, GDF15 may have a role in appetite regulation: it has been considered able to suppress food intake and determine loss of body weight, inducing nausea, vomiting and anorexia." (PMID 40464681, 2025). "GDF-15–GFRAL pathway activation induces anorexia and behavioural changes and enhances sympathetic nervous system (SNS) activity through the hypothalamus." (PMID 41294666, 2025). "GDF15 is elevated in cancer cachexia, chemotherapy-induced anorexia, hyperemesis gravidarum, and mitochondrial disorders." (PMID 40562759, 2025). "GDF-15 has been identified as a major factor in cancer cachexia, promoting muscle wasting and anorexia through the MIC-1/GDF-15-GFRAL signaling pathway." (PMID 39766045, 2024). "The findingspresented here illustrate the importance of potential mediators ofnausea and anorexia, such as GDF15, in our efforts to identify betterstrategies for CINV control." (PMID 37506293, 2023). "Exogenous administration of GDF15 induces nausea and emesis, suggesting malaise and conditioned food aversion as key components of GDF15-induced anorexia." (PMID 37474864, 2023). "For example, growth differentiation factor 15 (GDF-15) is produced by some tumors and activates anorexia via its receptor in the brainstem." (PMID 35941104, 2022). "Further, we investigate the possibility that GDF15 is responsible for the temporary anorexia after intense exercise." (PMID 33589633, 2021). "Mechanistic exploration suggested that GDF15 induced a lipolytic response in adipose tissue, independently of anorexia, which was mediated by the peripheral sympathetic nervous system (SNS)." (PMID 33464381, 2021).
Anorexia (continued). "Intriguingly, the day time restricted GDF15 induced anorexia leads to a “voluntary” time restricted feeding in the UCP1-tg mouse model." (PMID 33464381, 2021). "Given the role of exogenous GDF15 on malaise-related anorexia, we wondered if endogenously-derived GDF15 promotes a similar behavior." (PMID 33589633, 2021). "We consider that an increase in tumor burden contributed to GDF-15-related anorexia via solid stress and was related to systemic inflammation and worsened PS prior to the onset of body weight loss and sarcopenia." (PMID 34638326, 2021). "APC patients with high serum GDF-15 showed worsened performance, anorexia and elevations of inflammatory and tumor burden, signatures of cachexia, and activation of Akt and JNK in tumor GDF-15-producing pathways." (PMID 34638326, 2021). "On this basis, we concluded that patients in the high-GDF-15 group showed a clinically meaningful increase in the severity of anorexia compared with those in the low-GDF-15 group." (PMID 34638326, 2021). "One study suggested that the primary target for GDF15 is a distinct population of GFRAL/CCK neurons to engage the neural circuitry involved in anorexia and conditioned taste aversion." (PMID 34831213, 2021). "The degrees of anorexia in high- and low-GDF-15 groups corresponded to the upper and lower limits of mild anorexia, respectively." (PMID 34638326, 2021). "Mechanistic exploration suggested that GDF15 induced a lipolytic response in adipose tissue, independently of anorexia, mediated by the peripheral sympathetic nervous system (SNS)." (PMID 34831213, 2021). "The authors suggested that the primary target for GDF15 is a distinct population of GFRAL/CCK neurons which span the AP/NTS to engage the neural circuitry involved in anorexia and conditioned taste aversion." (PMID 33464381, 2021). "We found increased GDF-15 serum levels in cancer patients, and in particular in those with anorexia when compared to cancer patients with normal appetite." (PMID 33396237, 2020). "Based on our results, we suggest that the GDF15‐dependent diurnal anorexia represents the so far missing link between muscle mitochondrial dysfunction and remodeling of systemic energy homeostasis." (PMID 32026535, 2020). "Based on our observations, we confirm the role of GDF-15 in the pathogenesis of anorexia in cancer, although the mechanisms of action of this cytokine in cancer should be further unveiled also regarding its potential involvement in changes in muscularity." (PMID 33396237, 2020). "Previous work showed that GDF15 physiologically reduces oral nutrient intake through induction of anorexia, nausea, and vomiting." (PMID 32928255, 2020). "Recent studies in animal models and other settings have revealed that GDF15 drives anorexia, through induction of nausea, vomiting, and an aversive reaction to food." (PMID 32928255, 2020). "GDF15 activates GFRALAP/NTS neurons and supports conditioned taste and place aversions, while the anorexia it causes can be blocked by a monoclonal antibody directed at GFRAL or by disrupting CCK neuronal signalling." (PMID 32723474, 2020). "It was previously reported that young mice, where GDF11 was supraphysiologically expressed through plasmid insertion into the liver, lost weight due to anorexia and GDF15 activation, and displayed signs of frailty." (PMID 31637864, 2020). "In our study, the novel inflammatory cytokine Growth Differentiation Factor-15 (GDF-15) has been found elevated in patients with gastrointestinal and lung cancer and associated with anorexia." (PMID 33396237, 2020). "Mechanistically, we uncovered a GDF15‐dependent daytime‐restricted anorexia, whereas GDF15 is unable to suppress food intake at night." (PMID 32026535, 2020). "On the other hand, we uncovered that genetic ablation of GDF15 during muscle mitochondrial dysfunction prevented a daytime‐restricted anorexia, promotes a robust fat mass expansion, and abolishes white adipose tissue browning and insulin sensitivity." (PMID 32026535, 2020).
Anorexia (continued). "Available data suggest that neutralizing GDF-15 has the potential to not only ameliorate anorexia in cancer patients, but also to improve immunotherapies." (PMID 32508832, 2020). "GFRAL is exclusively expressed in the human brain stem and is responsible for GDF-15 mediated anorexia." (PMID 32508832, 2020). "On the other hand, some studies reported that anorexia is observed in the older hyperthyroid patients, suggesting the necessity of measurement of GDF15 in this age group." (PMID 30687235, 2018). "When overexpressed in disease, such as in advanced cancer, elevated serum MIC-1/GDF15 levels lead to an anorexia/cachexia syndrome." (PMID 24971956, 2014). "MIC-1/GDF15 levels of above 5,000–8,000 pg/ml cause severe anorexia/cachexia, and animal studies demonstrate that this is likely due to direct actions of MIC-1/GDF15 on feeding centres in the brainstem and hypothalamus." (PMID 23468844, 2013). "The possibility that increasing GDF15 in cancer patients may reflect not only anorexia and chronic inflammation but also mitochondrial dysfunction which we currently under investigation." (PMID 41016991, 2026). "Furthermore, cancer-associated anorexia/cachexia syndrome has been linked to high circulating concentrations of GDF15, while blockade of GDF15 or its receptor, GFRAL, reduces anorexia and weight loss in rodents." (PMID 40530451, 2025). "Both IL-6 and GDF15 have been functionally involved in cancer anorexia-cachexia." (PMID 40124481, 2025). "Nonetheless, the pro‐contractile effect of GDF15 is not necessarily in contrast with the promotion of anorexia and weight loss." (PMID 40464681, 2025). "In addition, GDF-15, a stress-responsive cytokine and a well-known endocrine-acting metabolic mediator, has been shown to promote daytime-restricted anorexia." (PMID 38318571, 2024). "Consequently, this challenges the notion that the circulating pleiotropic GDF15 exclusively activates GFRAL-expressing neurons in the AP/NTS, thereby being involved in anorexia and weight loss." (PMID 38474863, 2024). "It has also been found that GFRAL is localized on cholecystokinin (CCK) positive neurons; GDF15 activates CCK neurons, and GDF15-induced anorexia is attenuated by CCK signaling blockade, suggesting that GDF15 is mediated by anorexigenic signaling in CCK neurons in the brainstem." (PMID 39050134, 2024). "Thus, administration of exogenous GDF15 produces anorexia, aversion, conditioned taste avoidance (CTA) and pica in various animal models." (PMID 39737892, 2024). "In vivo studies in rats revealed that GRASP could attenuate GDF15-inducednausea and anorexia resulting from cisplatin." (PMID 37506293, 2023). "Despite previous observations suggesting a role for GDF15 in anorexia, we did not identify any association of GDF15 plasma levels with this trait." (PMID 35916366, 2022). "Furthermore, although total 24-h food intake remained unaffected, GFRAL signaling proved to be completely responsible for daytime-restricted anorexia elicited by GDF15." (PMID 36271504, 2022). "Additionally, TGF-β induces inhibin and activin, causing weight loss and muscle depletion, while MIC-1/GDF15, a member of the TGF-β superfamily, leads to anorexia and so, indirectly, to muscle wasting, acting on the hypothalamus center." (PMID 36078078, 2022). "It is not known if anorexia induced by endogenously elevated GDF15 is also linked to malaise states." (PMID 34831213, 2021). "Such pathological conditions are frequently accompanied by sickness-related anorexia and weight loss, and there is evidence linking GDF15 to non-homeostatic weight loss." (PMID 33589633, 2021). "ISR-ATF4/DDIT3-dependent GDF15 regulation may be important in many different diseases and the therapeutic effects of drugs related to anorexia, cancer, and metabolic disorders." (PMID 34877504, 2021). "Cancer patients express high circulating levels of GDF15, which contributes to anorexia/cachexia." (PMID 32427329, 2020).